CD38 (CD38 molecule)
Diseases named in the same sentence as CD38 in open-access papers (continued):
Sharing a sentence is not in itself a finding about the gene and the disease.
diabetes (continued). "Specifically, NSCLC patients with diabetes had lower percentages of CD38+ CD45+ lymphocytes than patients without diabetes." (PMID 35116020, 2021). "Instead, we found that CD95 expression was reduced on switched CD27+IgD− memory B cells in individuals with long-standing diabetes, consistent with the findings of a recent study by Hanley and colleagues, who also reported lower frequencies of CD24++CD38++ B cells in people with type 1 diabetes." (PMID 29881878, 2018). "CD38 is not reaching 100 CGC points which most likely is due to lack of the word "diabetes" in OMIM." (PMID 19575795, 2009). "However, the roles of CD38 in diabetes-induced cardiomyopathy were not evaluated." (PMID 37958991, 2023).
breast carcinoma (31 papers, 2002 to 2026). "Conversely, the expansion of circulating immunosuppressive CD19+ CD24+ CD38+ Bregs is linked to poor prognosis, underscoring the functional polarity of B cell subsets in breast cancer." (PMID 41364090, 2026). "Recent results also showed that Megamonas funiformis was associated with an increased risk of breast cancer, with 11.20% of this effect mediated by CD38 on IgD+ CD24−." (PMID 41180320, 2025). "Several studies have demonstrated that CD38 is associated with various types of cancer, including gastric, lung, and breast cancer." (PMID 40529366, 2025). "Mediation analysis revealed a positive causal relationship between IgD- CD38+ B cells and Glycerate levels, with the latter also exhibiting a positive causal relationship with the risk of breast cancer (p < 0.05)." (PMID 38826800, 2024). "Moreover, TLSs, CD3+ cells, and CD38+ cells in TLSs are associated with a good prognosis in patients with ER− recurrent breast cancer." (PMID 38133211, 2023). "The period from 2005 to 2015 marked a surge in CD38 research, with keywords such as breast cancer, colorectal cancer, prostate cancer, apoptosis, hematopoietic stem cells, therapy and gene expression gaining attention." (PMID 40529366, 2025). "IgD- CD27- AC and CD27 on IgD+ CD38- unsw mem (memory B cells) were identified as potential mediators of the causal relationship between critically ill COVID-19 and HER2-positive breast cancer." (PMID 40355230, 2025). "We identified CD38 on IgD+ CD24‐ as a mediator in the causal relationship between Species M funiformis and breast cancer." (PMID 39654239, 2024). "This means that CD38 on IgD+ CD24‐ plays a key mediating role in the link between breast cancer and M funiformis." (PMID 39654239, 2024). "Specifically, M funiformis and Species Prevotellamassilia can affect breast cancer by CD38 on IgD+ CD24‐ and HLA DR on CD33br HLA DR+ CD14‐, respectively." (PMID 39654239, 2024). "the IVW method results showed that CD45RA- CD4+ %CD4+ (p-value:1.37×10−6), CD8dim %T cell (p-value:4.62×10−43), BAFF-R on IgD+ CD38- unsw mem (p-value:6.93×10−5), CD27 on PB/PC (p-value:2.72×10−18) lowered the risk of breast cancer." (PMID 38327747, 2024). "For HER+ and ER−/HER2− recurrent breast cancers, TLSs were associated with longer PFS (p = 0.047), with the similar results for CD3+ cells (p = 0.023), CD38+ cells (p = 0.041), and CD68+ cells (p < 0.001) in TLSs." (PMID 38133211, 2023). "Based on the positive correlation between sPD-L1 level and the percentage of PD-1+CD19+CD24+CD38+ Bregs, we further investigated the function of sPD-L1 in the serum of breast cancer patients." (PMID 35935985, 2022). "CD38 was identified as a potential marker of T cell exhaustion by CyTOF in clear cell renal and breast cancers." (PMID 35725444, 2022). "In particular, CD38 expression in erythrocytes of patients with colorectal, gastric, pancreatic, and breast cancer was found to be significantly higher, with strong correlations to clinical factors such as CEA values, tumor stage, disease progression, lesion site, and degree of anemia." (PMID 40529366, 2025). "Moreover, critically ill COVID-19 exhibited causal relationships with CD27 on IgD + CD38- unsw mem, and the latter also demonstrated a positive causal relationship with the risk of HER2-positive breast cancer." (PMID 40355230, 2025). "We found that M funiformis had an effect on breast cancer through CD38 on IgD+ CD24‐." (PMID 39654239, 2024). "Our study found that M funiformis can have an effect on breast cancer through CD38 on IgD+ CD24‐." (PMID 39654239, 2024). "Finally, we discovered that “CD38 on IgD+ CD24‐” served as a mediator in the causal relationship between Species M funiformis and breast cancer, with a mediating ratio of 11.20%." (PMID 39654239, 2024). "Moreover, increased CD38+ HLA‐DR+ CD8 T cells have been observed in breast cancer patients achieving a pathologic complete response to neoadjuvant chemotherapy." (PMID 36208017, 2023).
breast carcinoma (continued). "Moreover, in the ER− locoregional recurrent breast cancer, TLSs, and immune cells (CD3+, CD68+, and CD38+) within TLSs were associated with improved PFS." (PMID 38133211, 2023). "CD38 inhibition using the anti-CD38 antibody daratumumab (Darzalex®, Genmab, Copenhagen, Denmark) together with nivolumab (anti PD-1 IgG4) is being analysed in a phase I/II study of 120 patients with advanced pancreatic, lung and breast cancer (NCT3098550)." (PMID 33546207, 2021). "In addition, the distribution of circulating CD4 + CD25 + FOXP3+ Treg lymphocytes and CD19 + CD24 + CD38 + B lymphocytes significantly increased in breast cancer patients compared with healthy controls using blood samples." (PMID 33726701, 2021). "Particularly, the identification of IgD- CD27- AC and CD27 on IgD + CD38- unsw mem as mediators signals towards intricate immune responses catalyzed by severe COVID-19 that might augment oncogenic processes in HER2-positive breast cancer." (PMID 40355230, 2025). "Conversely, IgD- CD38+ B cells displayed a negative causal relationship with Succinoyltaurine levels, and the latter also demonstrated a negative causal relationship with the risk of breast cancer (p < 0.05)." (PMID 38826800, 2024). "The different prognostic role of CD38+ cells within TLSs in different ER status found in this study may provide an explanation for the differential efficacy of chemotherapy and immunotherapy for breast cancer." (PMID 38133211, 2023). "We retrospectively included 112 patients with locoregional recurrent breast cancer, and hematoxylin–eosin staining and immunohistochemical staining (CD3, CD4, CD8, CD19, CD38, and CD68) were performed on locoregional recurrent tumor samples." (PMID 38133211, 2023). "In-situ studies of TIL in breast cancers demonstrate expression of the early activation markers CD38, 43 and 69, but show little or no expression of IL-2 receptor or IL-2 protein, suggesting anergic, tolerant T-cells." (PMID 11870535, 2002).
asthma (30 papers, 2008 to 2025). "Treatment of the hBSMCs with interleukin-13 (IL-13), an asthma-related cytokine, caused both an upregulation of CD38 protein and a downregulation of miR-140-3p." (PMID 33121100, 2020). "IL-13, an asthma-related cytokine, is capable of reducing miR-140-3p to cause an increase in CD38 expression." (PMID 33121100, 2020). "It is thus possible that the increased CD38 expression is a cause of the BSM hypercontraction observed in this animal model of asthma." (PMID 33121100, 2020). "Altered CD38 expression or enhanced cyclic ADP-ribosyl cyclase activity associated with CD38 contributes to human pathologies such as asthma, neoplasia, and neuroimmune diseases." (PMID 29576747, 2018). "Inflammatory cytokines such as IL-13 and TNF-α, which are implicated in asthma, augment CD38 expression and cADPR-mediated Ca2+ release and increase contractility of ASM." (PMID 29576747, 2018). "Inflammatory cytokines that are implicated in asthma upregulate CD38 expression and increase the calcium responses to contractile agonists in airway smooth muscle cells." (PMID 23213344, 2012). "CD38 has a role in airway hyperresponsiveness, a hallmark of asthma, since deficient mice develop attenuated airway hyperresponsiveness compared to wild-type mice following intranasal challenges with cytokines such as IL-13 and TNF-α." (PMID 18341691, 2008). "The cluster of differentiation 38 (CD38) target is known to be linked with an impaired immune system, and its inhibitors could be used in the treatment of asthma." (PMID 40231485, 2025). "Whether polymorphisms in the CD38 gene are associated with asthma in humans remain to be determined." (PMID 29576747, 2018). "The fact that CD38 expression is regulated by cytokines and transcription factors that are implicated in asthma, and inhibited by glucocorticoids which are a mainstay of asthma therapy makes this an attractive therapeutic target." (PMID 18341691, 2008). "When the expression of CD38 was examined in ASM cells, a molecule involved in AHR and airway inflammation in asthma, GC was unable to inhibit CD38 expression when cells were treated with the combination of TNFα and IFNγ." (PMID 36012240, 2022). "The results suggest that a significant reduction in CD38+ Th2A was observed only in all active groups, confirming the potential value of CD38+ Th2A cells as the new clinical biomarker of asthma." (PMID 36003397, 2022). "To explore the effect of CD38 in the regulation of airway remodeling in asthma, we downregulated CD38 expression in the lung tissue of asthmatic mice via intratracheal injection of adenovirus-expressing CD38 shRNA." (PMID 32889801, 2020). "Collectively, our findings indicate that CD38-meidated Ca2+ signaling contributes to airway remodeling that occurs in asthma." (PMID 32889801, 2020). "In conclusion, the findings of our study demonstrate that PTEN restricts airway remodeling that occurs in asthma through the downregulation of CD38-mediated Ca2+/CREB signaling." (PMID 32889801, 2020). "In conclusion, the current study demonstrated that the CD38 expression is negatively regulated by miR-140-3p in BSM cells and that miR-140-3p is downregulated concurrently with an upregulation of CD38 in BSMs of experimental asthma." (PMID 33121100, 2020). "In the present study, we have shown that the PTEN/CD38/Ca2+/CREB axis participates in airway remodeling in asthma." (PMID 32889801, 2020). "Although PTEN and CD38 have been reported to have crucial roles in the pathogenesis of asthma, the precise molecular mechanisms of PTEN and CD38 in airway remodeling throughout the pathogenesis of asthma remain poorly understood." (PMID 32889801, 2020). "Taken together, the results of our study have shown that the PTEN/CD38/Ca2+/CREB axis plays a critical role in airway remodeling that occurs throughout the progression of asthma." (PMID 32889801, 2020).
asthma (continued). "Both phosphatase and tensin homologue deleted on chromosome ten (PTEN) and cluster of differentiation 38 (CD38) have been suggested to be key regulators of the pathogenesis of asthma." (PMID 32889801, 2020). "In the present study, we explore the role of PTEN and CD38 in airway remodeling in asthma both in vitro and in vivo." (PMID 32889801, 2020). "Research on CD38 and its involvement in chronic inflammatory diseases, such as rheumatoid arthritis and asthma, indicates that the aberrant expression and hyperactivity of CD38 can tip immune responses towards disease pathology." (PMID 31878283, 2019). "Using pharmacological and genetic approaches in human cells and tissues, and murine models of asthma, we have demonstrated the contribution of CD38-cADPR to ASM Ca2+ signaling and contractility." (PMID 29576747, 2018). "We have also observed that among the cytokines that are implicated in asthma, TNF-α causes the greatest induction of CD38 expression in ASM cells." (PMID 29576747, 2018). "It is important to note that CD38 is also expressed on immune cells that are important in humoral and cell-mediated immune response in asthma." (PMID 29576747, 2018). "In murine models of asthma, we demonstrated the role of CD38 in allergen-induced airway inflammation and AHR." (PMID 29576747, 2018). "The involvement of CD38/cADPR signaling pathway in the pathogenesis of asthma at multiple levels of the process is supported by these observations." (PMID 23213344, 2012). "We propose that increased capacity for CD38 signaling in airway smooth muscle in asthma contributes to airway hyperresponsiveness." (PMID 23213344, 2012). "We propose that increased capacity for CD38/cADPR signaling in airway smooth muscle in asthma contributes to the development of airway hyperresponsiveness." (PMID 23213344, 2012). "The fact that inflammatory cytokines such as TNF-α and IL-13, a Th2 cytokine, are capable of increasing the capacity for CD38/cADPR signaling in human ASM cells indicates its potential role in human asthma." (PMID 23213344, 2012). "This pattern of differential induction of CD38 expression was seen in cells obtained from donors with a history of clinical asthma as well as from fatal asthmatics." (PMID 23213344, 2012). "In the context of asthma, CD38 promotes ASM hypercontractility and AHR." (PMID 37047327, 2023). "However, there is still a need to study the role of CD38 in the context of aging and corticosteroid insensitivity in asthma." (PMID 37047327, 2023). "Thus, our findings suggest that PTEN modulates airway remodeling in asthma through the regulation of CD38." (PMID 32889801, 2020). "This study aimed to elucidate the role of PTEN and CD38 in airway remodeling of asthma." (PMID 32889801, 2020). "However, the precise role and molecular mechanisms by which PTEN and CD38 are involved in airway remodeling throughout asthma pathogenesis remains poorly understood." (PMID 32889801, 2020). "An upregulation of CD38 protein was also demonstrated in BSMs of the murine asthma model used." (PMID 33121100, 2020). "Our findings demonstrate that PTEN inhibits ASM proliferation and migration in vitro and airway remodeling in vivo through the downregulation of CD38-mediated Ca2+/CREB signaling, which underscores the a key role of PTEN/CD38/Ca2+/CREB signaling in the molecular pathogenesis of asthma." (PMID 32889801, 2020). "For example, the following were included: the inhibition of glucocorticoids on degranulation of mast cells in allergic asthma, inhibition of the kinase ITK in a mouse model of asthma reduces cell death, and the inhibition of CD38 gene-modified dendritic cells on murine asthma development." (PMID 30210753, 2018). "ASM cells obtained from subjects who died from an episode of asthma or subjects with a history of stable asthma show significantly enhanced expression of CD38 (both transcript and protein) to low concentrations of TNF-α compared to expression in cells from nonasthmatics." (PMID 29576747, 2018).
asthma (continued). "Previous studies from our laboratory showed that CD38 expression and its enzymatic activities are augmented by TNF-α and IL-13, cytokines that are implicated in the pathogenesis of inflammatory airway diseases such as asthma." (PMID 18341691, 2008). "Therefore, our study suggests that CD38 is a crucial regulator of airway remodeling of asthma." (PMID 32889801, 2020). "Interestingly, CD38 has been suggested as a key regulator of asthma." (PMID 32889801, 2020). "Therefore, CD38 has emerged as an attractive drug target for the treatment of asthma." (PMID 32889801, 2020). "Moreover, in another study, highlighting the possibility that CD38 abnormalities could be a fundamental characteristic in asthma, TNF-α was shown to significantly increase CD38 expression in asthmatic ASM than in controls." (PMID 23577039, 2013). "To confirm the involvement of PTEN and CD38 in the pathogenesis asthma, we examined protein expression levels of PTEN and CD38 in the lung tissue of asthmatic mice using immunohistochemistry." (PMID 32889801, 2020). "In the lung, the link between CD38 and airway hyperresponsiveness (AHR) in allergic inflammation and asthma has been made evident." (PMID 31878283, 2019). "In a study on two young sisters with ASD, a deletion of 4p15.32, resulting in a BST1 (bone marrow stromal cell antigen 1)—CD38 fusion transcript and in disruption of CD38 expression, was identified only in the girl affected by more severe ASD and asthma." (PMID 28848387, 2017). "The impact of CD38 on NAD+ metabolism and sirtuins is an example of an aging-related mechanism that could contribute to airway inflammation in asthma." (PMID 37047327, 2023). "CD38 is ubiquitously expressed in ASM and its expression is augmented in asthma." (PMID 32889801, 2020). "Moreover, we showed that overexpression of PTEN markedly downregulated CD38 expression in TNF-α-stimulated ASM cells and in the OVA-induced mouse asthma model." (PMID 32889801, 2020). "CD38 is ubiquitously expressed in ASM and its expression is enhanced in asthma." (PMID 32889801, 2020). "Recent work has explored the role of CD38 in asthma and has suggested that increased CD38 expression causes hypercontractility in ASM cells from asthmatics although in our samples we saw no CD38 staining in the ASM layer." (PMID 29228930, 2017).